DKK1 (dickkopf Wnt signaling pathway inhibitor 1)
Diseases named in the same sentence as DKK1 in open-access papers (continued):
Sharing a sentence is not in itself a finding about the gene and the disease.
myeloma (147 papers, 2005 to 2025). "The serum levels of DKK-1 and sRANKL are not only associated with the stage of multiple myeloma but also closely correlated with the extent of osteolytic lesions." (PMID 41416066, 2025). "DKK1 hypersecretion has been linked to focal osteolytic bone lesions in patients with multiple myeloma." (PMID 40700291, 2025). "Expression of DKK1, an inhibitor of osteoblast differentiation, was found to be associated with the presence of bone lesions in patients with multiple myeloma." (PMID 39484215, 2024). "Nonetheless, the combination of anti‐LRP6 and anti‐DKK1 antibodies provided superior protection against myeloma‐induced bone loss, as well as providing superior protection against myeloma‐induced vertebral fracture compared to the single treatment approach." (PMID 36987921, 2023). "Another mechanism of growth is the secretion of endothelin-1 which downregulates DKK-1 and stimulates the secretion of the Wnt signaling pathways proven to be associated with lytic lesions and suppressing the growth of bone tissue in myelomas." (PMID 36230523, 2022). "The first association between Dkk-1 and osteolytic malignant bone disease was demonstrated in multiple myeloma then for OS and metastases of breast, prostate and lung cancers." (PMID 35277659, 2022). "DKK1 is secreted by myeloma cells and is associated with the presence of osteolytic lesions through inhibition of osteoblast differentiation." (PMID 36396631, 2022). "Nevertheless, the precise mechanisms underlying DKK1 overexpression in myeloma remain incompletely understood." (PMID 33420361, 2021). "DKK1 is closely associated with lytic bone lesions in patients with multiple myeloma, and neutralizing secreted DKK1 protected bone from damage in arthritic joints." (PMID 32220932, 2020). "DKK1 has previously been implicated in the osteolytic phenotype of multiple myeloma and elevated serum DKK-1 levels correlate with the presence of focal bone lesions as detected by MRI." (PMID 31083455, 2019). ", associated with a markedly increased expression of DKK1, a major inhibitor of osteoblastogenesis in multiple myeloma." (PMID 31083455, 2019). "For example, the expression of the WNT inhibitors, FRZB and DKK1 genes, is associated with osteolytic bone lesions in myeloma patients." (PMID 31748515, 2019). "The efficacy of an anti-DKK1 antibody has been investigated in multiple myeloma and prostate cancers that were associated with bone resorption." (PMID 29720122, 2018). "Genomic studies have shown that increased expression of DKK1 gene is associated with myeloma-induced bone disease." (PMID 29330358, 2018). "Elevated blood levels of DKK1 have been associated with multiple myeloma and various types of cancers including head and neck, lung, breast, liver, and bone cancers." (PMID 30028084, 2018). "Dikkof-1 (DKK-1) was identified as a significant contributor to local bone loss in myeloma through the inhibition of osteoblasts." (PMID 29056680, 2017). "The WNT mediated osteoblast inhibition has been shown to be implicated in bone metastasis from multiple myeloma patients where high levels of Dkk-1 a known WNT antagonist leads to impaired osteoblast function and lytic bone lesions." (PMID 26522007, 2015). "In multiple myeloma, increased levels of DKK-1 are associated with the presence of lytic bone lesions." (PMID 24528599, 2014). "For example, high Dkk1 activity is associated with pro-inflammatory bone loss in mouse myelomas, and inhibition of Dkk1 activity in a mouse model of rheumatoid arthritis results in greater bone formation." (PMID 24961798, 2014). "DKK-1 overexpression has been shown to correlate with lytic lesions in multiple myeloma and to induce bone loss." (PMID 23935976, 2013). "SOST mutations lead to severe HBM disorders, sclerosteosis and van Buchem disease, while DKK1 is shown to associate with bone lesions in multiple myeloma." (PMID 22487062, 2012).
myeloma (continued). "Increased DKK1 levels in bone marrow plasma and peripheral blood from patients with multiple myeloma are associated with focal bone lesions." (PMID 22792345, 2012). "A recent study has demonstrated that aberrant expression of Dkk-1 in myeloma cells was associated with increased bone erosion in human multiple myeloma." (PMID 21062498, 2010). "On the contrary, blockade of Wnt signaling in MSCs by DKK-1 has been shown to result in suppression of osteoblastic bone formation which contributes to the systemic bone loss and osteolytic bone lesions in myeloma." (PMID 20846389, 2010). "In this respect, an antibody directed against Dkk-1 reduced both bone loss and the myeloma tumour burden in a preclinical model." (PMID 19724279, 2009). "Myeloma cells cause bone loss by degradation and dysregulation of bone turnover via DKK1 and OPG." (PMID 38598843, 2024). "We show that anti‐LRP6 could be of therapeutic benefit to prevent myeloma‐induced bone loss, but superior protection against bone loss and reduced strength was demonstrated when used in combination with anti‐DKK1." (PMID 36987921, 2023). "Previously, the Wnt-antagonist DKK-1 has been implicated in reduced bone formation activity in multiple myeloma and in animal models of prostate cancer bone metastasis where it may regulate the transition between osteolytic and osteoblastic phenotypes." (PMID 24069136, 2013). "However, in a 5T2MM murine myeloma model treatment with the anti-DKK1 antibody BHQ880 also caused a reduction of osteolytic bone lesions but did not have any effect on tumor burden." (PMID 22363428, 2012). "Initially increased Dkk1 expression was found to be associated with the lytic bone lesions in patients with multiple myeloma, suggesting that Dkk1 might inhibit osteoblast differentiation or function." (PMID 20843343, 2010). "Dkk1 plays a major role in the development of bone lesions caused by multiple myeloma." (PMID 20653953, 2010). "The bone anabolic effects of anti-DKK-1 may also be associated with reduced myeloma burden." (PMID 37174109, 2023). "Therefore, understanding of the underlying mechanism for universal DKK1 expression in MM may provide tools for preventing this disease and the development of osteolytic bone lesions in myeloma." (PMID 33420361, 2021). "Thus, our model suggests that therapies directed against Dkk-1 may be useful in reducing bone loss and in slowing down the accumulation of tumour burden in patients with smouldering myeloma." (PMID 19724279, 2009). "In this context, 2 key myeloma markers, MYC and DKK1, as well as many other cancer-associated genes, including ADM, HDGF, IL15, HGF, STMN1, CDKN1B and CD82, were potentially regulated by the predicted ligands." (PMID 41056512, 2025). "DKK-1 is an inhibitor of the Wnt signaling pathway, and its expression level is significantly higher in multiple myeloma patients than in healthy controls." (PMID 41416066, 2025). "The serum levels of DKK-1 and sRANKL are significantly correlated with the stage of multiple myeloma (MM) and the extent of osteolytic lesions." (PMID 41416066, 2025). "In patients with multiple myeloma, the level of DKK1 was significantly increased, and the severity of skeletal lesions was significantly positively correlated with the DKK1 level." (PMID 38744806, 2024). "We aimed to examine the serum DKK-1 and sclerostin variations in newly diagnosed multiple myeloma (NDMM) patients at diagnosis and in the course of therapy, including autologous stem cell transplantation (ASCT)." (PMID 37445475, 2023). "In MM, DKK-1 is highly expressed by myeloma cells and regulates myeloma bone disease, defined as the displacement of hematopoiesis and the formation of osteolytic lesions via osteoblast inhibition and osteoclast activation." (PMID 37445697, 2023). "In vitro, pharmacological inhibition of DKK-1 prevented sclerostin upregulation by myeloma cells, and treatment with recombinant DKK-1 increased it." (PMID 37174109, 2023).
myeloma (continued). "In the case of multiple myeloma, myeloma cells secrete soluble mediators such as Dickkopf-related protein 1 (DKK1), activin A, and soluble frizzled-related protein 3 (sFRP3), which directly suppress osteoblastic bone formation." (PMID 36980681, 2023). "Preclinical studies in mouse myeloma models showed that targeting DKK-1 with neutralizing anti-DKK-1 antibodies increased osteoblasts, reduced multinucleated osteoclasts, and increased bone mass." (PMID 37174109, 2023). "Nevertheless, DKK1 was also upregulated in multiple myeloma (MM) bortezomib-resistant cells and was identified as a potential marker of a bortezomib-refractory phenotype." (PMID 37835450, 2023). "Dickkopf-1 (DKK1), another WNT inhibitor, contributes to myeloma-related bone disease as the production of DKK1 by myeloma cells increases the RANKL/OPG ratio." (PMID 36656634, 2023). "Although the reduction at the extraskeletal site with anti‐LRP6 alone requires further exploration, these data support the safe use of anti‐LRP6 alone or in combination with anti‐DKK1 to treat patients with myeloma." (PMID 36987921, 2023). "Unlike the DKK1/SOST dual antibody targeting two soluble antagonists, we chose to target both a membrane bound receptor and a soluble Wnt antagonist, DKK1, which is secreted by myeloma cells to suppress bone formation." (PMID 36987921, 2023). "In multiple myeloma, for instance, Dickkopf-1 (DKK1), an inhibitor of WNT-receptor-interaction, secreted by myeloma cells takes a key role in formation of osteolytic lesions by inhibiting osteoblast differentiation." (PMID 36982422, 2023). "When probing pathway level transcriptional changes in abnormal cells, we found aberrant expression of Wnt pathway members including overexpression of DKK1 in abnormal cells of precursor myeloma." (PMID 36396631, 2022). "While immunological blockade of Dkk-1 preserves bone in experimental models and multiple myeloma patients, this is the first time Dkk-1 blockade has been shown to preserve topology as well prevent bone loss." (PMID 35277659, 2022). "In Phase I clinical trials, anti-DKK1 antibodies (BHQ880) were tested for their potential to overcome the myeloma-mediated inhibition of osteoblasts." (PMID 35847862, 2022). "Further experiments from the same group in mouse murine myeloma models showed that vaccination with DKK1-DNA not only prevented mice from developing MM, but was also therapeutic against active MM." (PMID 36077618, 2022). "Myeloma cells contain detectable DKK1, which obstructs the differentiation of osteoblasts, promotes the proliferation of osteoblasts, changes the balance between osteoblasts and osteoclasts, and develops into osteolytic lesions." (PMID 35937845, 2022). "The antagonistic activity of DKK1 in myeloma can reduce osteolytic absorption, which is beneficial for controlling the growth of multiple myeloma." (PMID 35937845, 2022). "Immunoblockade of Dkk-1 has been successfully achieved in multiple myeloma and OS, but systemic Dkk-1 levels can be substantial, requiring large doses of antibodies." (PMID 35277659, 2022). "High expression of Dickkopf–Wnt-signalling pathway inhibitor-1 (Dkk-1) occurs in various cancers, including multiple myeloma and OS." (PMID 35277659, 2022). "On the other hand, myeloma cells secrete dickkopf-related protein 1 (DKK1) inhibits the Wnt/β-catenin signaling pathway and suppresses differentiation of mesenchymal stem cells (MSCs) into osteoblasts." (PMID 34991592, 2022). "Levels of DKK1 in plasma cells were shown to be correlated with the presence of lytic lesions in myeloma patients; these lesions can evolve into pathological fractures." (PMID 35355709, 2022). "Initial strategies for the blockade of Dkk-1 began with antibodies, and these showed promise in myeloma models and in humans, but antibodies must be given at large doses given that Dkk-1 levels in humans can reach hundreds of ng mL−1." (PMID 35277659, 2022).
myeloma (continued). "DKK1 levels are elevated in patients with MM, which in turn suppresses the differentiation of osteoblasts in favor of osteoclasts and promotes myeloma-related bone destruction." (PMID 35681747, 2022). "Myeloma cells produce excessive levels of dickkopf-1 (DKK1), which mediates the inhibition of Wnt signaling in osteoblasts, leading to multiple myeloma (MM) bone disease." (PMID 33420361, 2021). "The vaccine targeting PD-L1 and DKK1 showed efficacy in the mice model of multiple myeloma, which required the function of CD8+CD11c+ dendritic cells and CD8+ T cells." (PMID 34093545, 2021). "Marrow plasma from patients with myeloma with >12 ng/ml of DKK1 interrupts the osteoblastic differentiation of murine mesenchymal stem cells (MSCs) in vitro." (PMID 33420361, 2021). "A neutralizing antibody against DKK1 prevents the development of osteolytic bone disease in MM and promotes bone fracture healing, and it simultaneously inhibits myeloma growth in vivo." (PMID 33420361, 2021). "Taken together, our results demonstrated that hypoxia induces HIF-1α to promote MMSET expression in myeloma cells, ultimately contributing to the upregulation of DKK1." (PMID 33420361, 2021). "We then collected the supernatant from cell cultures of hypoxia-treated myeloma cells with different secreted DKK1 levels, and we added it to OB medium for culture of bone marrow MSCs." (PMID 33420361, 2021). "The application of DKK-1 inhibition by monoclonal antibodies has been analyzed in the treatment of the characteristic osteolytic lesion produced by multiple myeloma progression." (PMID 34451907, 2021). "In summary, this study revealed that the cooperation of the p38-CREB cascade with MMSET promotes DKK1 expression in response to hypoxia in myeloma cells." (PMID 33420361, 2021). "Taken together, our findings reveal that hypoxia and a cytogenetic abnormality regulate DKK1 expression in myeloma cells, and provide an additional rationale for the development of therapeutic strategies that interrupt DKK1 to cure MM." (PMID 33420361, 2021). "Another DKK1 antibody BHQ880 had completed the clinical phase II experiment for multiple myeloma in year 2020." (PMID 34803487, 2021). "DKK1 is frequently found to be overexpressed in the myeloma microenvironment of patients with serious bone disease, but it is highly restricted in normal tissues." (PMID 33420361, 2021). "The experimental model of multiple myeloma showed that anti-Dkk-1 antibody treatment reversed the inhibitory effect of Dkk-1 on osteoblasts’ differentiation and bone formation, thus reducing bone loss." (PMID 34122101, 2021). "Knockdown of CREB in myeloma cells alleviated the suppression of osteoblastogenesis by myeloma-secreted DKK1 in vitro." (PMID 33420361, 2021). "In a pre-clinical study using SCID-rab mice, it was demonstrated that anti-DKK1 decreased osteoclastogenesis and promoted new bone formation by stimulating osteoblast activity, in both myeloma-involved and uninvolved bones." (PMID 34201396, 2021). "DKK1 has also been exploited in an immunotherapy setting in a myeloma mouse model and also with primary myeloma samples, and an early phase 1 study (NCT03591614) is going to start soon." (PMID 33409156, 2020). "In the context of multiple myeloma, the Dkk-1 in the bone microenvironment contributed to the development of focal osteolytic lesions and indirectly facilitated multiple myeloma metastases to bone." (PMID 33384994, 2020). "Myeloma cells in MM patients extensively secrete DKK1 to inhibit proliferation of mesenchymal stem cells (MSC) or early-stage osteoprogenitors, leading to decreased bone formation at osteolytic bone." (PMID 31963554, 2020). "Secretion of the cytokines Dickkopf 1 (DKK1) and Frizzled related protein 2 (sFRP-2) by myeloma cells contributes to bone resorption as well." (PMID 33634031, 2020). "Phase I and phase II clinical trials have been performed to test the efficacy of anti-DKK1 antibodies on myeloma and myeloma-induced skeletal events." (PMID 32733380, 2020).
myeloma (continued). "The elevated levels of Dkk-1 were correlated with a poor prognosis in patients suffering from multiple myeloma, prostate cancer, hepatocellular carcinoma and non-small cell lung cancer (NSCLC)." (PMID 33384994, 2020). "Dickkopf-1 (DKK1), expressed by the myeloma cells and BMSC, antagonizes the WNT-pathway, blocks the differentiation of osteoblasts, and high DKK1 expression in the bone marrow is associated with more severe MBD." (PMID 32751464, 2020). "Excess Dkk1 produced by myeloma cells suppresses osteoblast differentiation, resulting in lytic bone lesions in multiple myeloma." (PMID 33287247, 2020). "Since patients with multiple myeloma (MM) have shown high DKK1 levels that were correlated with osteolytic bone damage, an anti-DKK1 neutralizing agent has been developed and clinically used in MM." (PMID 31963554, 2020). "The human anti-DKK-1 antibody BHQ880 is expected to be a promising target for skeletal-related events in multiple myeloma because DKK-1 is expressed by multiple myeloma cells and plays an important role in osteolytic bone disease." (PMID 31137666, 2019). "Impaired osteoblast differentiation in myeloma has previously been attributed to excessive Wnt inhibition, with particular implication of Wnt inhibitors Dkk1 and sclerostin." (PMID 31586071, 2019). "Wnt inhibitors Dkk1 and sclerostin are elevated in the serum and bone marrow of patients with myeloma, and blocking their action improves myeloma bone disease pre-clinically." (PMID 31586071, 2019). "As part of a phase I/II clinical trial, an antibody to DKK1 was found to increase osteoblast differentiation in-vitro upon co-culture with multiple myeloma cells." (PMID 29867053, 2018). "Blood levels of DKK-1 have been shown to be elevated in myeloma patients and are correlated with the extent of bone disease." (PMID 30544512, 2018). "Myeloma cells are known to produce Wnt signaling inhibitors such as soluble Frizzled-related protein 2 and 3, and Dickkopf-1 (DKK-1), hereby impeding the normal osteogenesis." (PMID 30409995, 2018). "Dickkoff-1 (DKK-1), a soluble inhibitor of the canonical Wnt signaling pathway, is secreted by myeloma cells and acts as an inhibitor of osteoblast development." (PMID 30544512, 2018). "The undifferentiated MSCs expressed IL6 that increased the growth of the myeloma cells, which subsequently produced more Dkk1, establishing a positive feedback loop." (PMID 29642534, 2018). "As a result, DKK1 is regarded as one of the TSAs for MM and a potentially important antigenic target for anti-myeloma immunotherapy." (PMID 29416605, 2018). "In contrast, DKK-1 overexpression has been reported in various tumors, including human hepatoblastomas, Wilms’ tumors, multiple myelomas, and hormone-resistant breast cancers." (PMID 28938611, 2017). "It has been reported that DKK1 produced by myeloma cells inhibits osteoblast differentiation in vitro, and increased DKK1 levels in bone marrow plasma and peripheral blood correlate with the presence of lytic bone lesions in myeloma patients." (PMID 29108326, 2017). "Although there are many similarities in cellular and molecular mechanisms of tumor growth and bone disease between myeloma and solid tumor bone metastases, there are also numerous examples of differences, including the relative contributions of PTHrP and Dkk1." (PMID 28241871, 2017). "Specifically, rodent MM models of bone explants loaded with MM cells and treated with humanized anti-DKK1 antibodies (BHQ880) showed reduce myeloma burden and/or bone erosion." (PMID 27367730, 2016). "The same authors reported that myeloma cells expressed high levels of DKK-1, which suggested that inhibition of Wnt signalling was associated with osteolytic lesions." (PMID 26785768, 2016). "In contrast, serum DKK1 was also reported to be significantly lower in cancers, such as in multiple myeloma responding to anti-myeloma treatment, clear cell renal cell carcinoma and so on." (PMID 26799283, 2016).